IL6 (interleukin 6)
Diseases named in the same sentence as IL6 in open-access papers (continued):
Sharing a sentence is not in itself a finding about the gene and the disease.
depression (continued). "In depression there is an increase in pro-inflammatory cytokines (interleukine-1β (IL- 1β); IL-6, and IFNγ (interferon-gamma)) and the acute phase of depression is due to high levels of pro-inflammatory cytokines such as IL-6 and IL-1β." (PMID 23204984, 2012). "The inflammation in depression, which is characterized by increased levels of cytokines like interleukin-1 and 6 (IL-1, IL-6), and tumor necrosis factor (TNF), may cause the occurrence of somatic symptoms of depression." (PMID 22839681, 2012). "Serum samples from 65 perimenopausal women, 41 with depression and 24 without depression, were assessed for serum IL-6, TNFα and IL-10 by conventional enzyme-linked immunosorbent assays." (PMID 22490187, 2012). "IFN-α may also indirectly stimulate the hypothalamic-pituitary-adrenal axis, which is known to be overactive in depression, by inducing cytokines (e.g. IL-6), that activate this system." (PMID 22701688, 2012). "IL-6 may induce production of corticotropin-releasing hormone, resulting in hypercortisolemia, which in turn might contribute to depression." (PMID 21701640, 2011). "The mechanisms of depression are multifactorial, but there is growing evidence that systemic inflammation may result in depression and IL-6 appears to play a particularly important role in humans and in animal models of depression." (PMID 20305715, 2010). "Nursing research focused on identifying patients at risk of experiencing painful CIPN and reduced QOL may wish to consider including other symptoms, such as depression and fatigue, which are known to be influenced by cytokine concentrations, particularly IL-6." (PMID 21994811, 2010). "Therefore, IL-6, CRP, and TNF-α may represent promising targets in research on the pathomechanisms of depression and in the search for new diagnostic strategies." (PMID 40507778, 2025). "Indeed, compelling evidence supports robust connections between depression and inflammation in IA, as depression drives peripheral and central inflammation and several cytokines implicated in depression also play influential roles in IA, including CRP, TNF-α and IL-6." (PMID 38749000, 2025). "Chronic social defeat stress (CSDS) induces microglial activation of P2X7Rs and subsequent IL-6 release, which binds to IL-6 receptors on astrocytes, triggering apoptotic pathways, reducing astrocyte numbers, and impairing their function—contributing to anxiety- and depression-like behaviors." (PMID 40936908, 2025). "Furthermore, growing evidence suggests that individuals with depression also exhibit elevated levels of circulating cytokines like IL-6, IL-1β, TNF-α, IFN-α, prostaglandin E2 (PGE2), and chemokine CCL2, as well as acute-phase proteins such as C-reactive protein (CRP)." (PMID 40573262, 2025). "Additionally, some inflammatory factors, such as interleukin-6 (IL-6) and tumor necrosis factor-alpha (TNF-α), may be associated with depression and cognitive decline." (PMID 40861349, 2025). "In rodent models of diabetes-associated depression, activation of indoleamine 2,3-dioxygenase (IDO)—a key enzyme in tryptophan metabolism—results in decreased hippocampal serotonin (5-HT) levels and elevated pro-inflammatory cytokines such as TNF-α, IL-1β, and IL-6." (PMID 41299994, 2025). "Interestingly, even in human blood, cumulative meta-analysis revealed that there is no consistent association with IL-1β and TNFα whilst IL-6 showed significance with depression in humans." (PMID 40179065, 2025). "However, studies in mice demonstrated that TNF-α secreted from hippocampal microglia induces working memory deficits by acute stress, whereas increased IL-6 was found in microglia from mice that had undergone repeated social defeat stress, as well as in patients with treatment-resistant depression." (PMID 40722844, 2025). "In addition to astrocytes, IL‐6 may contribute to the pathological process of depression by influencing neural function and neurogenesis." (PMID 39888279, 2025).
depression (continued). "Moreover, reduced systemic inflammation reflected by lower IL-6 and CRP levels may decrease neuroinflammation and improve mood regulation, as chronic inflammation is implicated in depression pathogenesis." (PMID 40927565, 2025). "Furthermore, chronic inflammation in depression activates pro-inflammatory cytokines like IL-6 and TNF-α, which not only contribute to the stress response but may also promote erythropoiesis by affecting the bone marrow environment." (PMID 39797347, 2025). "A recent longitudinal study of major depressive disorder identified a low baseline red blood cell count as a significant predictor of suicidal ideation trajectories, suggesting erythrocyte-mediated modulation of neuroinflammatory circuits (e.g., IL-6 and TNFα)." (PMID 40977981, 2025). "However, we did not observe an association between IL-6 and the likelihood of developing clinical depression." (PMID 39902492, 2025). "Adolescents with MDD face an elevated risk of appetite loss, which may correlate with clinical symptoms such as depression severity and negative life events, as well as elevated IL-6 level." (PMID 40438334, 2025). "However, we found weak correlations between anxiety and IL-6 concentrations which could support the potential psychological symptom link with IL-6 given that anxiety and depression often coexist and may have overlapping aetiology." (PMID 41050477, 2025). "In addition to IL-1B, IL-6 is of particular importance in the study of depression." (PMID 40313235, 2025). "Increased levels of pro-inflammatory cytokines like IL-6, tumor necrosis factor-α (TNF-α), and IL-1β, which are implicated in starting inflammatory processes, are influenced by the CNS through several mechanisms that affect organs and, in turn, lead to depression." (PMID 39859327, 2025). "The present study suggested that appetite loss might be associated with a range of clinical symptoms (especially depression severity and negative life events) and levels of inflammatory cytokines (especially IL-6)." (PMID 40438334, 2025). "Studies have shown that schizophrenia disorder is linked to altered glucose and fat metabolism, and the infusion of IL-6 in IL-6 knock-out mice failed to induce schizophrenia disorder, indicating that IL-6 elevation could be a general feature of major depressive disorders like schizophrenia." (PMID 40843259, 2025). "Building on the finding that activated microglia release IL‐6, leading to astrocyte apoptosis in vitro, we further investigated whether IL‐6 released by microglia mediates astrocyte atrophy and apoptosis and contributes to anxiety‐ and depression‐like behaviors in vivo." (PMID 39888279, 2025). "A subset (n = 29) of the present TRD sample (n = 40) was previously included in a study that examined whether changes in inflammation occur over the course of ECT (T1, T2 and T3) and whether changes in IL-6 or CRP (from T1 to T2) predicted global improvement in depression severity." (PMID 39834556, 2025). "For example, in PsA, depression has been associated with serum IL-6, but not IL-17A or CRP." (PMID 39959848, 2025). "Importantly, the DI-GM score, which specifically captures dietary components favoring gut microbial health, showed even stronger inverse associations with depression, anxiety, and inflammatory markers, including CRP, IL-6, and fecal calprotectin, compared to the MIND score." (PMID 40927565, 2025). "According to our obtained data, it can be assumed that IL-6 can influence the onset of depression in patients with pSS, with the note of potential bidirectional relationship of inflammation and depression and that patients with pSS may also have a genetic basis for the onset of depression." (PMID 40822847, 2025). "Notably, researchers have demonstrated that an increase in IL-6 levels may further promote depression particularly in individuals affected by comorbidities and/or diseases such as multiple sclerosis and cancer." (PMID 40313235, 2025).
depression (continued). "Polymorphisms in the IL-6 gene, such as the -174G>C variant (rs1800795), have historically been shown to modulate transcriptional activity and are associated with heightened inflammatory responses to psychosocial stress and increased risk for CVD and depression." (PMID 41373439, 2025). "Many studies also detected a decrease in symptoms of pain, weakness, and depression if IL-6 blockers were used, but it is difficult to identify whether the effect on one symptom reduced the other symptoms as well or whether IL-6 is responsible for the occurrence of each symptom individually." (PMID 40699818, 2025). "Depression, for instance, may accelerate cancer progression through endocrine and immunological changes, particularly chronic inflammation, with increased production of interleukin-6 (IL-6), C-reactive protein and TNFalpha." (PMID 39754194, 2025). "According to research data, in patients with somatic diseases (e.g., dermatosis) who have not previously suffered from psychiatric disorders, pro-inflammatory cytokines (including IL-1, IL-6, TNF-α) may cause true major depressive disorders (coexisting with somatic symptoms)." (PMID 40278530, 2025). "Thus, managing IL-6/IL-6R levels in the circulatory system could control both inflammation and depression." (PMID 41274868, 2025). "Also, the higher IL-6 levels in depressed rats, herein, could be attributed to depression-induced alteration of local brain activity." (PMID 38315652, 2024). "Interestingly, serum IL-6 is also a marker of depression in the general population, further supporting the idea that inflammation may be final common pathway to Brain FADE syndrome." (PMID 38304427, 2024). "In addition, previous studies have shown that IL-6 levels are elevated in patients with depression." (PMID 39074257, 2024). "Compared to MRL/lpr IL-6 WT, IL-6 KO mice exhibited improved novelty preference on object placement (45.4% vs 60.2%, p < 0.0001) and object recognition (48.9% vs 67.9%, p = 0.002) but equivalent performance in tests for anxiety-like disease and depression-like behavior." (PMID 38600510, 2024). "IL-6 encodes a kind of cytokine, which plays a role in the process of inflammatory response and B-cell maturation by binding to receptors IL6R and IL6ST, whose dysregulation can precipitate multiple events relevant to depression, such as serotonin depletion and neurodegenerations." (PMID 39408591, 2024). "Furthermore, individuals with depression have significantly higher levels of inflammatory cytokines, such as interleukin-1 (IL-1), interleukin-4 (IL-4), interleukin-6 (IL-6), and tumor necrosis factor-alpha (TNF-α), which are also important mediators in the pathogenesis of asthma." (PMID 39479594, 2024). "The last hypothesis of depression regards inflammation, according to which, the development of depression is accompanied by increased levels of proinflammatory cytokines, such as interleukin-1β, interleukin-6, and tumor necrosis factor alpha (TNF-α)." (PMID 39201362, 2024). "Unlike clinical research results, our study revealed no causal relationship between ss and depression and anxiety from a genetic perspective, maybe elevated IL-1, IL-6, TNF-α and IFN-α levels are not related to the pathogenesis of SS." (PMID 39479595, 2024). "Indeed, IL-6 has been shown to have a role in the production of pain and fatigue in RA and may also have a role in depression." (PMID 38340224, 2024). "Conversely, high IL-6 baseline levels in patients with depression were negatively correlated with the response to SSRIs or serotonin-norepinephrine reuptake inhibitors (SNRIs), supporting the hypothesis of different subgroups with different pathomechanisms in the genesis of depressive disorders." (PMID 38796643, 2024).
depression (continued). "Elevated serum levels of miR-9-5p in individuals with depression stimulate the polarization of M1 microglia, triggering excessive release of pro-inflammatory cytokines such as interleukin-1β (IL-1β), interleukin-6 (IL-6), and tumor necrosis factor-α (TNF-α), thereby exacerbating neurological damage." (PMID 38528957, 2024). "Furthermore, IL-6 has been associated with increased activity of the HPA axis by increasing cortisol levels and coordinating biological pathways underlying stress and stress-induced depression." (PMID 38474387, 2024). "This suggests that IL-6 may lead to reduced L-selectin levels in the context of depression." (PMID 39415236, 2024). "Therefore, individuals with depression and periodontitis appear to share an alteration in the production of various pro-inflammatory factors (IL-1, IL-6, TNF-α), which, on the one hand, increases the individual’s systemic inflammatory load and, on the other hand, increases neuroinflammation." (PMID 39124790, 2024). "However, while most results point towards no changes in immune-inflammatory markers, two trials using the same probiotic strains in different supplements reported decreased hs-CRP levels in patients with depression, and reduced IL-6 levels in patients with multiple sclerosis." (PMID 39048549, 2024). "Interleukin 6 plays a role in the development and physiological or somatic consequences of major depression, and the levels of two types of cytokines, namely interleukin 6 and tumor necrosis factor α (TNFα), are significantly higher in patients with major depression." (PMID 37692307, 2023). "This oxidative stress and increased depression lead to demyelination and cerebral atrophy, accompanied by elevated concentrations of inflammatory mediators such as tumor necrosis factor (TNFα) and specifically interleukin IL-6, along with IL-1α and IL-1β, in the serum and CSF." (PMID 37693246, 2023). "Interestingly, ZW inhibited diabetes-induced anxiety and depression by minimizing the neuroinflammatory response by decreasing NfκB, IL-1β, and IL6 mRNA levels and the number of TNF-α- and GFAP-immunostained neurons and serum level of TNF-α and CRP because of its antioxidant power." (PMID 38105928, 2023). "Chronic shame may be involved in the relationship between SSS and health since SSS and chronic shame have similar psychological, physiological, and health correlates including low self-esteem, elevated levels of interleukin-6 (IL-6) which is a marker of inflammation, depression, and SRH." (PMID 37842010, 2023). "The relationship between sleep disturbance and depression might be explained in light of the inflammation hypothesis which highlights an association between poor sleep quality, increased levels of inflammatory cytokines such as interleukin-6 and C-reactive protein, and depression." (PMID 37069886, 2023). "Indeed, other studies have found that depression is associated with both CAD and cognition and increases the risk of developing CAD, likely due to its pro-inflammatory state with increased levels of IL-1, IL-6 and TNF-alpha." (PMID 37627038, 2023). "Interestingly, the tears of patients with depression showed higher levels of inflammatory cytokines IL-6, IL-17 and TNF-a, which may take part in dry eye inflammation." (PMID 36674068, 2023). "Furthermore, sleep deprivation has been demonstrated to further contribute to the onset and progression of depression through activation of the sympathetic nervous system and β-adrenergic signaling, which increased the level of inflammatory markers such as IL-6 and C-reactive protein." (PMID 37731854, 2023). "Indeed, high levels of pro-inflammatory cytokines like interleukin-6 (IL-6), tumor necrosis factor-α and interleukin-1β (IL-1β), may promote the onset of depression, as well as inflammatory markers like C-reactive protein (CRP)." (PMID 37587401, 2023).
depression (continued). "The cytokine hypothesis suggests that in depression, the number of pro-inflammatory cytokines such as IL-6, IL-1β and TNF-α is increased, while the number of anti-inflammatory cytokines such as IL-10 and TGF-β is decreased, tilting the overall immune response toward inflammation." (PMID 37387537, 2023). "Therefore, this study aimed to investigate the relationship between IL-6 levels, amygdala emotional reactivity, and depression/anxiety, considering gene-psychosocial stressor interactions, in a sizeable community sample with various levels of depression/anxiety." (PMID 37324818, 2023). "Longitudinal twin studies and meta-analyses indicate that elevation in IL-6 may be a risk factor leading to depression, rather than a consequence of depression." (PMID 37280232, 2023). "The current study provides evidence on the relationship between IL-6 secretion, amygdala emotional reactivity, and depression, indicating that disrupted IL-6 secretion could affect greater depressive symptoms, being modulated by amygdala hyporeactivity and gene-psychosocial stressor interactions." (PMID 37324818, 2023). "However, till date the association of CRP and IL-6 with depression and cardiometabolic risks in GDM has not been studied." (PMID 37365247, 2023). "There is evidence that depressive disorder is characterized by increased activity of immune cells and increased levels of proinflammatory cytokines, especially pivotal cytokines such as interleukin (IL)-1β, IL-6, tumor necrosis factor (TNF)-α, and interferon (IFN)-γ." (PMID 37834806, 2023). "Furthermore, IL-6, tumor necrosis factor-alpha (TNF-α), and IL-1β are implicated in the pathophysiology of depression, and individuals with depression often have elevated circulating IL-1β, IL-6, and TNF with reduced levels of interferon-gamma (IFN-γ), IL-10, and IL-4." (PMID 35546876, 2022). "In particular, IL-6 plays an important role in the inflammatory hypothesis of depression." (PMID 36358455, 2022). "Furthermore, high TNF-α (P=0.044, P=0.176 after adjustment), high IL-1β (P=0.012, P=0.048 after adjustment), increased IL-6 (P=0.010, P=0.040 after adjustment), and increased IL-17 (P=0.010, P=0.040 after adjustment) were correlated with increased depression severity grade." (PMID 35239774, 2022). "This indicates that IL-6 activity, rather than generalized inflammation as a whole, could at least in part underly the associations of smoking with depression." (PMID 36057695, 2022). "Finally, we detected an association between IL-6 and negative attributional cognitive bias of depression." (PMID 36187407, 2022). "In addition, IL-6 and TNF-α are considered crucial systemic inflammatory factors causing chronic obstructive pulmonary disease complications such as osteoporosis, endothelial cell injury, and depression." (PMID 35892720, 2022). "Our previous publication revealed that depressive patients with pain had higher plasma levels of IL-6 and granulocyte-macrophage colony stimulating factor (GM-CSF) than those without pain, suggesting pain increases inflammatory response in patients affected by depression." (PMID 35370832, 2022). "Furthermore, TNF‐α, IL‐1β, IL‐6, and IL‐17 were all positively associated with HADS‐A score (all P < 0.05), anxiety occurrence (all P < 0.05), HADS‐D score (all P < 0.05), and depression occurrence (all P < 0.05) in NSCLC survivors, while the correlation‐coefficients were weak." (PMID 34697903, 2022). "Finally, we conducted a multivariable Mendelian randomization (MVMR) analysis to examine the associations between genetically-predicted smoking behavior and risk of depression after adjusting for genetically-predicted proxies of generalized inflammation (CRP) and IL-6 activity." (PMID 36057695, 2022).